RAD51AP1 (RAD51 associated protein 1)
Diseases named in the same sentence as RAD51AP1 in open-access papers (continued):
Sharing a sentence is not in itself a finding about the gene and the disease.
tumor (27 papers, 2012 to 2025). "RAD51-associated protein 1 (RAD51AP1) not only enhances tumor stemness but also exerts an influence on the tumor immune microenvironment." (PMID 38037058, 2023). "To explore the potential role of RAD51AP1 in the tumor microenvironment of ESCC, we assessed the associations between the expression of RAD51AP1 and the infiltration level of immune cells." (PMID 36197550, 2022). "Meanwhile, the lack of data in the tumor microenvironment also restrained further validation of the RAD51AP1 effect on tumor-associated immune at a multi-faceted level." (PMID 36468013, 2022). "In present study, tumour‐infiltrating immune cells results manifested high‐RAD51AP1 samples were infiltrated in Th2 cells, which was considered as the pro‐tumour cell implicated in severe disease." (PMID 33314567, 2021). "The anti-correlation signature was present separately in the tumour and normal samples, suggesting a direct causal dysregulation of RAD51AP1 by hsa-miR-140-3p in the ovary." (PMID 22452920, 2012). "We discovered a novel function of RRM1 in DNA damage repair, wherein it regulates HR and promotes tumor cell survival by modulating the transcription of RAD51AP1." (PMID 39695160, 2024). "In our study, we made the novel discovery that increasing RRM1 expression can stimulate the transcription and expression of RAD51AP1, leading to enhanced HR efficiency and increased radiation resistance in tumor cells." (PMID 39695160, 2024). "We then performed a multivariate analysis to compare tumor stage, and age, with the levels of RAD51AP1 in OvCa." (PMID 35207688, 2022). "The study found RAD51AP1, RAD54L, and EME1 to be hub genes in HR patterns associated with immunotherapy response and tumor progression." (PMID 35559013, 2022). "In summary, these findings partially supported that RAD51AP1 participated in the immune response in ESCC tumor microenvironment." (PMID 36197550, 2022). "According to TCGA-BRCA data, the expression of the positive genes of risk score (HJURP, IFI27, RAD51AP1, EZH2, DNMT3B, SLC7A5, DBF4 and USP18) in tumors was higher than that in normal and tumor-adjacent tissues." (PMID 36341435, 2022). "The results revealed that RAD51AP1 was significantly upregulated in almost all tumor types, including ESCC." (PMID 36197550, 2022). "Meanwhile, the effect of RAD51AP1 on immune cell infiltration in the tumor microenvironment and its correlation with tumor heterogeneity, microsatellite instability (MSI), tumor mutational burden (TMB), and RNA modification have not been reported yet." (PMID 36468013, 2022). "Genes dysregulated according to tumour grade included CDC45 and RAD51AP1, which are both associated with the ALT pathway." (PMID 32899298, 2020). "In vivo imaging analysis at days 7, 14 and 21 revealed that knocking down RAD51AP1 significantly inhibited the tumor volume compared to that in the Lenti-N.C." (PMID 31532757, 2019). "Knocking down RAD51AP1 significantly inhibited tumor volume in an intracranial EGFRvIII-positive GBM model and prolonged survival time." (PMID 31532757, 2019). "Decreased RAD51AP, encoding an enhancer of RAD51, observed in tumours from ECR patients is consistent with this suggestion, as genetic ablation of RAD51AP1 leads to enhanced sensitivity to chromosome aberrations upon DNA damage." (PMID 26810418, 2016). "Within the anti-correlated pairs, one pair: hsa-miR-140-3p/RAD51AP1, was anti-correlated in both tumour and normal samples with opposite expression levels in tumor/normal, implying the dysregulation of a direct microRNA/mRNA mechanism." (PMID 22452920, 2012). "For example, the expression level of RAD51AP1 was found to be strongly anti-correlated with the expression of hsa-miR-140-3p, which was significantly down-regulated in the tumour samples." (PMID 22452920, 2012).
tumor (continued). "Consequently, the elevated levels of E2F1 in the nucleus promote the transcription of RAD51AP1, thus enhancing HR-mediated DNA damage repair and ultimately improving tumor cell survival post-IR exposure." (PMID 39695160, 2024). "Taken together, these findings indicated that RAD51AP1 could regulate cell growth and metastasis to promote the tumor development of ESCC in vitro." (PMID 36197550, 2022). "At this stage of understanding, we believe that RAD51AP1 may have an essential role in the tumor microenvironment (TME) and may become a candidate indicator to distinguish between so-called “hot” or “cold” tumors." (PMID 36468013, 2022). "The tumor stemness enhancing and tumor immune microenvironment affecting functions of RAD51AP1 might compose its carcinogenesis mechanism." (PMID 36468013, 2022). "Under certain assumptions, we speculate that RAD51AP1 might also affect tumor cells’ malignant phenotype via RNA modification regulation." (PMID 36468013, 2022). "However, recent studies have shown that RAD51AP1 was highly expressed in several tumor tissues, and its high expression also indicated a poor prognosis." (PMID 36468013, 2022). "The role of RAD51AP1 in enhancing tumor stemness, regulating RNA modification, and affecting the tumor immune microenvironment might compose its carcinogenesis mechanism." (PMID 36468013, 2022). "In our study, we observed the downregulation of RAD51 in tumor samples, which may account for the RAD51AP1 increase." (PMID 31159852, 2019). "Thus we speculate that the genome homeostasis-maintaining function of RAD51AP1 may also improve tumor heterogeneity." (PMID 36468013, 2022). "High expression of RAD51AP1 might contribute to tumor progression of ESCC." (PMID 36197550, 2022). "RAD51AP1 might also be positively correlated to tumor heterogeneity in multiple cancers." (PMID 36468013, 2022). "RAD51AP1 may serve a role in DNA repair and tumor cell proliferation." (PMID 32963620, 2020). "The results showed that the mRNA expression levels of hub genes (PBK, KIF2C, NUF2, KIF20A, RAD51AP1 and DEPDC1) in tumor samples (EAC, ESCC) were significantly higher than in normal samples (P < 0.05)." (PMID 33403046, 2021). "While the expression levels of SEPT3, RAD51AP1, and EXO1 are higher in tumor-bearing patients, while ABHD14B is lower." (PMID 34646403, 2021). "The results indicated that tumor purity significantly and positively correlated with PBK (R= 0.24, P= 1.13e-03), NUF2 (R= 0.267, P= 2.75e-04), RAD51AP1 (R= 0.275, P= 1.83e-04), and DEPDC1 (R= 0.166, P= 2.56e-02) expression." (PMID 33403046, 2021). "It was also usually positively correlated to PD-L1, tumor heterogeneity, TMB, and MSI, suggesting that RAD51AP1 may become a potential predictive biomarker for ICIs therapy." (PMID 36468013, 2022). "Likewise, we looked into HPV-positive HNSCC tumours with different grades in the TCGA and found that higher grade tumours appeared to have higher expression of BRD4, CDKNA2, RAD51AP1 and CDC6 with EGFR expression was lesser in higher tumour grades." (PMID 36333293, 2022). "Tumour infiltrating lymphocytes (TILs), including T cells, B cells and NK cells, that exhibited anti‐tumoural functions, especially CD8 + and CD4 + T cells were infiltrated in low‐level RAD51AP1 group." (PMID 33314567, 2021). "The anti‐tumour cells including central memory CD4 T cell, central memory CD8 T cell, Th1 cell, Th17 cell, etc were higher in low‐level RAD51AP1 group; however, Th2 cell and the pro‐tumour cell were enriched in high‐level RAD51AP1 group." (PMID 33314567, 2021). "These transformation-encoding CNAs, together with deletion of TNF on 6p, and amplification of RAD51AP1 and ITPR2 on 12p, are correlated with a suppression of cell cycle arrest, senescence, and apoptosis, i.e., a tumor cell’s immortality, and a patient’s shorter survival time." (PMID 25875127, 2015).
adenocarcinoma (2 papers, 2019 to 2024). A common cancer characterized by the presence of malignant glandular cells. "Loss of RAD51AP1 leads to defective homologous recombination and genome instability, while upregulation of RAD51AP1 has been associated with a poor prognosis in several kinds of adenocarcinoma." (PMID 38216586, 2024).
cardiovascular disorder (1 paper, 2022). A disease involving the cardiovascular system. "Exploration of the DEGs identified by silencing RAD51AP1 in SKOV3 cells demonstrates many associations with endocrine and cardiovascular disorders." (PMID 35207688, 2022).
RAD51AP1 also shares sentences with these, for which no sentence is quoted: colon cancer (2 papers); gastric cancer (2); hepatocellular carcinoma (2); acute myeloid leukemia (1); adrenocortical carcinoma (1); colon adenocarcinoma (1); endocervical adenocarcinoma (1); lung adenocarcinoma (1); lymphoma (1); metabolic disease (1); metastatic cancer (1); pancreatic adenocarcinoma (1); rectum adenocarcinoma (1); thymoma (1); thyroid carcinoma (1); uterine carcinosarcoma (1); uterine corpus endometrial carcinoma (1); xeroderma pigmentosum (1).